Y_RNA (Y RNA )
Gene: Miscellaneous RNA gene on chromosome 9 (37,160,137 to 37,160,237, forward strand). Ensembl gene ENSG00000200502.
Homologues: Orthologues: chimpanzee Y_RNA (96% identical), macaque Y_RNA (93% identical). Paralogues in human: RNY3 (90% identical), Y_RNA (90% identical), RNY3P1 (89% identical), Y_RNA (89% identical), Y_RNA (88% identical), Y_RNA (87% identical), Y_RNA (86% identical), Y_RNA (85% identical), RNY3P11 (84% identical), RNY3P14 (84% identical), RNY3P2 (84% identical), Y_RNA (84% identical), and 96 more.